KATNA1 (katanin catalytic subunit A1)
Description:
Catalytic subunit of a complex which severs microtubules in an ATP-dependent manner. Microtubule severing may promote rapid reorganization of cellular microtubule arrays and the release of microtubules from the centrosome following nucleation. Microtubule release from the mitotic spindle poles may allow depolymerization of the microtubule end proximal to the spindle pole, leading to poleward microtubule flux and poleward motion of chromosome. Microtubule release within the cell body of neurons may be required for their transport into neuronal processes by microtubule-dependent motor proteins. This transport is required for axonal growth.
Tractability: Small molecule: a structure with a bound ligand is known. PROTAC: UniProt records ubiquitination sites on it; ubiquitination databases record sites on it; its protein half-life has been measured.
Target class: Isomerase; Enzyme
Gene: Protein-coding gene on chromosome 6 (149,594,873 to 149,648,972, reverse strand). Ensembl gene ENSG00000186625.
Subcellular location: Cytoplasm; Midbody; Cytoplasm, cytoskeleton, microtubule organizing center, centrosome; Cytoplasm, cytoskeleton, spindle pole; Cytoplasm, cytoskeleton, spindle
Subcellular location (Human Protein Atlas): Centriolar satellite; Nucleoplasm
Gene Ontology:
Molecular function: microtubule binding; microtubule severing ATPase activity; protein binding; protein heterodimerization activity; ATP hydrolysis activity; ATP binding
Biological process: cytoplasmic microtubule organization; microtubule severing
Cellular component: centriolar satellite; cytoplasm; katanin complex; midbody; mitotic spindle pole; spindle; spindle pole; microtubule cytoskeleton; centrosome; mitotic spindle
Genetic constraint (gnomAD): Loss-of-function variants: 30 observed, 54.06 expected, observed/expected ratio (o/e) 0.55, 90% interval 0.41 to 0.75. The upper end of that interval is the gene's LOEUF score, 0.75, which puts it in group 3 of 6, group 1 being the genes least tolerant of losing a copy. Missense variants: 448 observed, 576.03 expected, observed/expected ratio (o/e) 0.78, 90% interval 0.72 to 0.84. Synonymous variants: 167 observed, 187.48 expected, observed/expected ratio (o/e) 0.89, 90% interval 0.79 to 1.01.
Homologues: Orthologues: chimpanzee KATNA1 (99% identical), macaque KATNA1 (99% identical), rabbit KATNA1 (97% identical), pig KATNA1 (97% identical), guinea pig KATNA1 (96% identical), rat Katna1 (93% identical), dog KATNA1 (93% identical), mouse Katna1 (93% identical), tropical clawed frog katna1 (85% identical), zebrafish katna1 (77% identical), Drosophila melanogaster Kat60 (55% identical), Drosophila melanogaster kat-60L1 (47% identical), and 3 more. Paralogues in human: KATNAL1 (67% identical), KATNAL2 (35% identical), FIGNL1 (33% identical), VPS4A (32% identical), VPS4B (32% identical), SPAST (31% identical), FIGN (28% identical), ATAD1 (24% identical), FIGNL2 (24% identical).
Diseases named in the same sentence as KATNA1 in open-access papers:
KATNA1 is named in the same sentence as 7 diseases in open-access papers, as found by Europe PMC text mining. Sharing a sentence is not in itself a finding about the gene and the disease. The quoted sentences say what the papers report.
Infertility (1 paper, 2023). "No aspect of the infertility phenotype appeared worse than loss of KATNAL2 in isolation, revealing that KATNA1 and KATNAL2 do not have compensatory function in male germ cell development." (PMID 37882691, 2023).
lymph node metastasis (1 paper, 2021). "Increased KATNA1 expression correlates with lymph node metastasis and advanced TNM stages." (PMID 34414183, 2021).
cancer (2 papers, 2021 to 2024). A tumor composed of atypical neoplastic, often pleomorphic cells that invade other tissues. "KATNA1, STMN1 and KIF2C are key proteins involved in microtubule dynamics, with implications in cancer progression and potential targets for anticancer drug development." (PMID 39175104, 2024).
KATNA1 also shares sentences with these, for which no sentence is quoted: breast carcinoma (1 paper); neurological disorders (1); prostate carcinoma (1); tumor (1).